ALB (albumin)
Diseases named in the same sentence as ALB in open-access papers (continued):
Sharing a sentence is not in itself a finding about the gene and the disease.
diabetes (continued). "Therefore, the amount of total Mg and Ca may lower with the albumin decreasing in CKD patients with diabetes." (PMID 26273297, 2015). "Female sex, co-morbid illnesses (diabetes, myocardial infarction, CABG, pulmonary edema, malignancy, any serious illness) were associated with incident CVC use whereas increasing age, hemoglobin, albumin, BMI and hypertension were associated with incident AVF/AVG (data not shown)." (PMID 24576140, 2014). "Additionally, the ECWBIA/TBWWatson ratio was associated with traditional risk factors for kidney disease progression, including age, male sex, diabetes mellitus, higher pulse pressure, resistant hypertension, lower eGFR, lower serum albumin level, and higher proteinuria level." (PMID 25435421, 2014). "This discrepancy may be attributed to the low percentage (17.7%) of patients with diabetes in our study, as serum albumin level has been reported to be lower in diabetic PD patients and may become a confounding factor in studies recruiting a high population of diabetic patients." (PMID 24667814, 2014). "In vivo, the proportion of glycated albumin in healthy persons is in the range of 1%–10%; this proportion may increase two- to three-fold in diabetes mellitus and is used as a short-to-intermediate-term marker for glycemic control in diabetes." (PMID 25407721, 2014). "This is compared to a rate of 26% in the 2283 patients without diabetes, where there is a significant association of urine protein or albumin testing with CKD documentation (44% vs. 24%, p < 0.0001), but the association was no longer significant after adjustment for eGFR, gender, and race." (PMID 24885821, 2014). "On renal function, about 77% of persons with known diabetes had a urinary albumin:creatinine ratio of <30 mg/g as compared to 65% in the U.S. studies, which could be due to the shorter duration of diabetes in our study (7.7 years vs. 11.4 years, respectively) and better glucose control." (PMID 23637851, 2013). "However, it has been shown that many patients with diabetes may still develop DN, even if their urinary albumin levels are within the normal range." (PMID 24250725, 2013). "In the logistic regression modelling, SBP, serum uric acid, CRP and diabetes were significantly associated with albuminuria and it was marginally significant for GGT (p = 0.054) while there was significantly inverse relationship between serum albumin and albuminuria." (PMID 23947772, 2013). "Analogously, the induction of diabetes in eNOS deficient mice results in a podocytopathy and rapid increase in albumin excretion in the absence of light microscopic features of additional renal injury, with the rise in albuminuria being unresponsive to VEGFR-2 blockade." (PMID 24063000, 2013). "And data from an Epidemiological Study on the Insulin Resistance syndrome (DESIR) study also demonstrated that elevated urinary albumin exertion predicted the 9-year risk of diabetes in men, independent of baseline or early development of metabolic abnormalities or insulin resistance." (PMID 23805186, 2013). "The logistic prediction model with the coefficient as non-response following HBV vaccination, diabetes mellitus, old age, and low albumin level could significantly predict infection-cause mortality (sensitivity = 0.842, specificity = 0.937)." (PMID 22935561, 2012). "However, other pathologies such as trauma, sclerodermia, diabetes, bacterial or viral infections, end-stage renal disease, liver cirrhosis, brain ischemia, peripheral arterial disease, and cancer are able to influence the binding site of cobalt in albumin." (PMID 22084701, 2011). "Thus, multiple studies now confirm that proteinuria is a graded risk factor for CVD independent of GFR, hypertension and diabetes and that this risk extends down into ranges of albumin excretion generally considered “normal”." (PMID 25013588, 2011).
diabetes (continued). "However, it is possible that C-peptide may have exerted a direct effect on the glomerular handling of albumin, as suggested by the studies of renal function in animals with experimental diabetes." (PMID 20535267, 2010). "History of TB, dialysis efficiency, use of Vitamin D supplements, serum albumin and zinc levels were not proved to influence significantly the risk for TB, in contrast to: advanced age (>65 years), BMI, diabetes mellitus, tuberculin reactivity, healed TB lesions on chest X-ray and time on dialysis." (PMID 19895701, 2009). "In multivariate regression models, the associations between sRAGE and 24 hour albumin excretion (β = 0.22, p = 0.02) as well as esRAGE and age (β = 0.24, p = 0.01) were independent of glucose control, diabetes duration, body-mass-index, glomerular filtration rate, blood pressure and gender." (PMID 17343760, 2007). "The mFI-5 assesses five comorbidities (diabetes, hypertension, COPD, heart failure, functional dependence), while the GNRI evaluates nutritional status using albumin and body weight." (PMID 41782056, 2026). "T2DM: type 2 diabetes mellitus, ASCVD: atherosclerotic cardiovascular disease, UACR: urine albumin-creatinine ratio, eGFR: estimated glomerular filtration rate." (PMID 41602226, 2026). "The study found significant correlation between the prevalence for DR and the duration of diabetes, HbA1c, CRP and urine albumin levels." (PMID 41541002, 2026). "The Boruta algorithm identified 9 key factors, including diabetes duration, uric acid, HbA1c, NLR, smoking status, SCR, LDH, Albumin, and hypertension." (PMID 40538804, 2025). "In comparative studies, elderly recipients often present with lower BMI, absence or well-controlled diabetes mellitus, lower international normalized ratio (INR), and higher serum albumin levels at the time of waitlist registration." (PMID 40900573, 2025). "This yielded eight significant predictors: age, CI, ABI, WBC, ALB, UACR, family history of diabetes, and DPN." (PMID 40661746, 2025). "The red blood cell distribution width to albumin ratio (RAR), which reflects systemic inflammation and nutritional imbalance, has shown predictive value in chronic kidney disease and diabetes." (PMID 40630492, 2025). "Recently, metabolic biomarkers, such as glycated albumin (GA) and methylglyoxal (MGO), have been successfully employed for the management of diabetes and its complications." (PMID 40144552, 2025). "MFS is the MASLD fibrosis score that predicts liver fibrosis based on age, body mass index (BMI), platelets, albumin, AST/alanine aminotransferase (ALT) and impaired fasting glucose (IFG) diabetes status." (PMID 40264510, 2025). "This study aims to evaluate the correlation between the uric acid (UA) to albumin (ALB) ratio (UAR) and carotid atherosclerosis (CAS) in patients with type 2 diabetes mellitus (T2DM), as well as to assess the predictive value of UAR for CAS." (PMID 40153388, 2025). "Model 2 adjusted for gender, age, while Model 3 included further covariables such as diabetes, uric acid, serum creatinine, BUN, hemoglobin, albumin, method of catheter placement, and eGFR." (PMID 40082960, 2025). "The model included baseline serum albumin level, illness severity scores (SOFA, quick SOFA), AKI stage, presence of sepsis, diabetes mellitus, vasopressor use, exposure to nephrotoxic drugs, mechanical ventilation, and patient age." (PMID 41291529, 2025). "The SAFE score formula includes age, body mass index, diabetes, platelets, AST, ALT, and globulins (total protein minus albumin)." (PMID 40093587, 2025). "CCN2/CTGF, NT-proBNP, age, serum albumin, MHD vintage, high-sensitivity C-reactive protein, smoking, and diabetes mellitus were significant predictors." (PMID 41373510, 2025). "Other different predictors of poor outcome that have been demonstrated, in the literature include age, site of occlusion, NIHSS score, history of diabetes mellitus, TICI score, number of passes, use of tPA, hematocrit, and serum albumin." (PMID 41541867, 2025).
diabetes (continued). "Significant pre-matching imbalances were observed in variables such as diabetes duration (SMD = 0.17), BMI (SMD = 0.26), and albumin (SMD = 0.20)." (PMID 40672825, 2025). "There were statistically significant differences among the three groups regarding age, duration of diabetes, prevalence of hypertension, SBP, HDL-C, ALB, ALT, AST, UA, BUN, eGFR, and UAR levels (all P < 0.05)." (PMID 40153388, 2025). "HbA1C, age, urine creatinine, ALB, urea, SCr, UA, TG, LDL-C, eGFR, Hb, PT, duration of diabetes mellitus, and hypertension levels." (PMID 41393943, 2025). "Comparative analysis revealed significant between-group differences (P < 0.05) in age, diabetes status, operative duration, blood transfusion, internal fixation use, postoperative NLR, and CRP/ALB ratio." (PMID 41019129, 2025). "Duration of diabetes, MODD, urinary albumin-to-creatinine ratio, and macroangiopathy were independently associated with SAF (adjusted R2 = 0.265)." (PMID 41381649, 2025). "Type 2 diabetes mellitus is accompanied by halogenated stress as neutrophilic MPO generates highly reactive hypochlorous acid (HOCl), which can modify serum albumin (Cl-HSA)." (PMID 39875729, 2025). "The independent variables included age, smoking, diabetes, BSA, BMI, tumor staging, tumor location, hepatic metastasis, lung metastasis, ALB, CEA, and the number of chemotherapy cycles." (PMID 39895779, 2025). "The four groups differed in age, sex, race, PIR, smoking, alcohol consumption, hypertension, diabetes, CVD, platelet count, ALT, albumin, creatinine, and LDH (all p < 0.05)." (PMID 40171273, 2025). "A total of 13 predictors were initially selected in the training set: sex, diabetes, AST/ALT, ALT, ALB, A/G, DBIL, HDL-C, TyG-BMI, WHR, BMI, SBP, and height." (PMID 41189900, 2025). "This study also found that diabetes patients have higher levels of CRP and albumin than healthy individuals." (PMID 40792303, 2025). "Among participants with diabetes, DKD was defined using the albumin-to-creatinine ratio (ACR ≥30 mg/g) and estimated glomerular filtration rate (eGFR <60 mL/min/1.73 m2)." (PMID 39842843, 2025). "Factors including hypertension, diabetes mellitus, body weight, BMI, ALT, AST, albumin, triglycerides, fasting insulin, HDL-C, steatosis grade, and fibrosis stage were significantly associated with MASH (all p < 0.05)." (PMID 40361915, 2025). "Patients with more advanced CKD were older, had higher urinary albumin–creatinine ratio (UACR) and blood pressure, and were more likely to have diabetes mellitus (DM)." (PMID 39950153, 2025). "In terms of laboratory parameters, patients with DPN exhibited significantly lower levels of Lymph, Hb, ALB, and TC, while showing elevated levels of Neut, TBil, SCR, LDH, UA, and longer duration of diabetes (all P < 0.05)." (PMID 41234226, 2025). "Significant differences were observed between the two groups in terms of age, ethnicity, PIR, education, marital status, WWI, albumin, ALT, AST, smoking history, and the prevalence of hypertension, diabetes, and CKD." (PMID 40013161, 2025). "The linear regression was adjusted for age, gender, ethnicity, smoking status, alcohol consumption, hypertension, diabetes, BMI, waist circumference, Ghb, CRP, ALB, CR, WBC, RBC, and HGB." (PMID 40271127, 2025). "Both biochemical parameters (Glucose, Triglyceride, HDL, Albumin, WBC) and clinical characteristics (BMI, diabetes duration >10 years, insulin use) were independently associated with glycemic deterioration." (PMID 41008733, 2025). "A component analysis showed that BMI and diabetes contributed 72% of the variance in NFS, whereas fibrosis-specific markers such as albumin contributed only 14%." (PMID 40954485, 2025). "Significant differences were observed between the two groups in terms of age, white blood cell count, platelet count, serum albumin levels, GCS score, smoking history, diabetes history, chest trauma, craniocerebral surgery, and endotracheal intubation." (PMID 40708949, 2025).
diabetes (continued). "Ultimately, 13 variables were included: BMI, neutrophils, platelets, albumin, SII, PNI, AISI, multiple pregnancies, multiparas, diabetes, hypertension, alcohol consumption and smoking." (PMID 40606469, 2025). "The following parameters were studied: age, gender of patients, duration of diabetes, number of diabetic ketoacidosis (DKA) episodes, serum creatinine, serum urea, urine albumin excretion (UAE), glycated hemoglobin (HBA1c) and mean RRI of both kidneys." (PMID 40370868, 2025). "For example, we project the LYFT for a White male with a BMI of 30–35, 1 year of dialysis, diabetes, a PRA of 0%–1%, and albumin of 3.5–4 mg from the model showing the trends by age group and year in the first quadrant (top)." (PMID 39841979, 2025). "A nomogram model comprising six variables—gender, blood urea nitrogen (BUN), Shock Index (SI), albumin, SOFA score, and diabetes mellitus—was developed." (PMID 40297154, 2025). "Subsequently, univariate and multivariate logistic regression analyses were performed to further refine the variable selection, and 9 independent predictors were ultimately identified: diabetes, ALT, ALB, A/G, HDL-C, TyG-BMI, BMI, SBP, and height." (PMID 41189900, 2025). "The feature importance for the combined model identified the 5 most contributing features for predicting diabetes stages, comprising three molecular markers—miR342, NFKB1, and miR636—and two biochemical markers, the albumin-to-creatinine ratio and HDLc." (PMID 40533788, 2025). "In patients with diabetes, a reduction in the glomerular filtration rate (GFR) and/or increased excretion of albumin in the urine for at least three months defines the diagnosis of CKD, as in the case of other patients." (PMID 39684653, 2024). "Statistical analysis results suggested that the age, proportion of cardiovascular disease, proportion of diabetes, NT-proBNP and CRP were higher, while BMI, serum albumin, EF and RRF were lower in the pleural effusion group." (PMID 38241413, 2024). "These predictors include age, diabetes mellitus, history of cerebrovascular disease, smoking, ASA classification, albumin level, tumor number, and surgical approach." (PMID 38777824, 2024). "Above results had demonstrated a positive association (p < 0.05) between mortality and variables containing age, sex, CKD etiology, diabetes, tumor, AST, AST/ALT ratio, C-Reactive protein, hemoglobin, albumin, prealbumin, inhalation drugs, and vaccination." (PMID 39555696, 2024). "The binary logistic regression analysis was conducted with PDR as the independent variable, and systolic blood pressure, diastolic blood pressure, course of diabetes, FBG, 2hPBG, HbA1c, BUN, Cr, UA, urinary albumin and TC as covariants." (PMID 38545017, 2024). "Participants with lower LDL-C and total cholesterol levels had higher proportion of diabetes, higher CRP levels, and lower serum albumin levels at baseline." (PMID 38626061, 2024). "Multivariate analysis highlighted the significance of parameters such as albumin, total bilirubin, AFP, the presence of diabetes mellitus, and a tumor size < 5 cm in the PNS-positive group compared to the PNS-negative group." (PMID 38674198, 2024). "In the separate analyses conducted by sex and adjusting for age, diabetes prevalence, LVMI, LVEF, cDBP, cPP, and serum albumin levels, the interaction effect was significant only in women (P = 0.010)." (PMID 38177252, 2024). "Many of the 16 predictors identified (e.g., age at diagnosis and visit, BMI, eGFR, blood urea, urine albumin, HbA1c, and HDL) tend to worsen as the duration of diabetes increases." (PMID 39685880, 2024). "Among these factors, BMI, ALB, Hb, TG, HDL‐C, HbA1c, CRP >10 mg/L, age, duration of diabetes, Wagner grades 3–5, and using insulin were significantly associated with malnutrition in diabetic patients." (PMID 39364802, 2024).
diabetes (continued). "In thecontext of Type 2 Diabetes Mellitus (T2DM), the term "adjusted calcium" refers to a calculated value that considers the impact ofalterations in serum albumin levels on total calcium concentrations." (PMID 38352911, 2024). "BMI, hypertension, preoperative diabetes mellitus, HBsAg positivity, AFP, ALB, GGT, FPG, TG, HDL-C, tumor size, number of tumors, TG/HDL-c, and TyG-BMI differed significantly between the high and low TyG groups." (PMID 39537878, 2024). "Furthermore, the progression of streptozotocin-induced diabetes, characterized by elevated renal function indices (blood urea nitrogen, creatinine), liver function indices (bilirubin, alkaline phosphatase) and decreased levels of albumin and globulin, was mitigated following pCel administration." (PMID 39055304, 2024). "Sex, presence of diabetes, use of β-blockers, HD vintage, BMI, CCI scores, Kt/Vurea, UFV, serum albumin concentrations, calcium levels, and CHA2DS2-VASC scores were not significantly different between the two groups." (PMID 38673676, 2024). "Retinol binding protein 4 (RBP-4), alongside glycated albumin (GA), glycated human serum albumin (GHSA) and the GHSA to human serum albumin (HSA) ratio, belongs to a group of specific biomarkers that can predict the diabetes condition even better than glucose." (PMID 38392020, 2024). "The BMI, ALB, Hb, TG, HDL‐C, HbA1c, age, and duration of diabetes were significantly different between different nutritional status groups." (PMID 39364802, 2024). "Statistical differences were observed in the distribution of age, history of hypertension and diabetes, and HDL, ALB, GLB, ALT, AST, LDH, and TG levels (p values < 0.05)." (PMID 38521854, 2024). "It was found that the model fit was good (Hosmer-Lemeschow test p = 0.152) and the influences of albumin, HDL cholesterol, hypertension, diabetes mellitus and alcohol consumption were statistically significant (p < 0.05)." (PMID 38682035, 2024). "Using unifactorial and multifactorial joint construction of ROC curves for analysis, ALB (AUC = 0.896), HDL-C (AUC = 0.728), hypertension (AUC = 0.660), diabetes mellitus (AUC = 0.588), and alcohol consumption (AUC = 0.603) had diagnostic potential for IS." (PMID 38682035, 2024). "The distinguishing factors were age, sex, comorbidities (including diabetes and tumor), and levels of AST, AST/ALT ratio, C-reactive protein, hemoglobin, albumin, and prealbumin." (PMID 39555696, 2024). "Significant differences between the two groups were noted in several including TSAT, ALT, albumin, serum iron, hemoglobin, HS-CRP, age, BMI, gender, race, PIR, marital status, smoking status, drinking status, hypertension and diabetes (all p < 0.05)." (PMID 39280001, 2024). "Notably, cancer patients with albumin levels ≤ 4.2 g/dL were characterized by older age, a higher likelihood of being female, a greater propensity for being overweight, and a statistically significant increase in the prevalence of diabetes mellitus, hypertension, cardiovascular disease, and anemia." (PMID 38500655, 2024). "Two of the most used scores to diagnose fibrosis are FIB-4 (AST, ALT, age, and platelet count) and NFS (age, BMI, diabetes mellitus/IFG, albumin, platelet count, and De Ritis ratio)." (PMID 38473907, 2024). "We observed significant differences in Age, Smoking status, Diabetes, Hypertension, AHM, ALT, TP, ALB, PAB, CR, cCa, PTH, and TG among the different groups." (PMID 38435391, 2024). "The between-group differences in age, diabetes mellitus status, CVD status, BMI, Hb, ALB, hs-CRP, NLR, TG, prealbumin and 4-h D/Pcr were statistically significant (all P < 0.05)." (PMID 38918730, 2024). "Older patients had lower serum albumin (ALB) levels and higher low-density lipoprotein cholesterol (LDL-C) levels, had diabetes, had several calcification sites, and had CHD/stroke had worse survival rates, which can better predict mortality." (PMID 39026232, 2024).